INS (insulin)
Diseases named in the same sentence as INS in open-access papers (continued):
Sharing a sentence is not in itself a finding about the gene and the disease.
Hyperglycemia (continued). "Treatment with insulin after infection improved some of these complement effectors compared with persistent hyperglycemia." (PMID 25610878, 2014). "Gene-deletion experiments in mice have demonstrated that Gck is essential for insulin secretion and maintenance of glucose homeostasis and that reduction in Gck gene dosage (Gck+/− mice) is sufficient to induce mild hyperglycemia." (PMID 25497096, 2014). "The Stepping Up trial has been designed as a translational study, testing the implementation of a known efficacious intervention (insulin for treating hyperglycemia) into real world practice in primary care." (PMID 24528528, 2014). "A better understanding of the roles played by hyperglycemia and insulin in the regulation of innate immunity will guarantee a more rational and an effective insulin treatment for these patients." (PMID 24899891, 2014). "Hyperglycemia, or high blood glucose, is a condition in which an excessive amount of glucose circulates in the blood which develops when the body has too little insulin or when the body cannot use insulin properly." (PMID 24864247, 2014). "Two patients intravenously received 2 units of regular insulin for managing sustained hyperglycemia." (PMID 25295519, 2014). "Glinides, short-acting insulin secretagogues, enhance early-phase insulin secretion, thereby reducing postprandial hyperglycemia." (PMID 26237486, 2014). "Hyperglycemia resulting from defective insulin secretion, resistance to insulin action, or both is a critical pathogenesis of DM." (PMID 25197672, 2014). "In animal models, maternal hyperglycemia resulted in perinatal hyperglycemia and increased hypothalamic insulin levels, followed by findings of permanent dysplasia of hypothalamic nuclei regulating food intake and metabolism in the offspring." (PMID 24689042, 2014). "The UKPDS demonstrated that a 10-year intensive glucose control by sulphonylureas or insulin achieved an 11% reduction by tight hyperglycemia control of HbA1c below 7.0% vs. the conventional care of HbA1c below 7.9%." (PMID 25121493, 2014). "As a result, this model induces a form of hyperglycemia (peripheral resistance to insulin, moderate reductions in insulin levels) that is a reasonable simulation of what occurs in critically ill patients." (PMID 24886999, 2014). "The ability of pancreatic β-cells to synthesize and secrete insulin is the key to overcome the hyperglycemia and maintain the glucose homeostasis in the settings of insulin resistance." (PMID 25646092, 2014). "Elevated GCs in rodents induce peripheral tissue abnormalities that affect liver and skeletal muscle insulin sensitivity/signalling, thereby promoting hyperglycemia." (PMID 24642683, 2014). "In our study, in line with expectations, we observed severe hyperglycemia and concomitantly very low fasting plasma insulin level (below the lower limit of detection) after streptozotocin injection." (PMID 24701589, 2014). "Third, the lack of laboratory measurements is a limit; DM is a complicated disease that is characterized not only by hyperglycemia but also by other metabolic impairments (eg, levels of insulin or IGFs)." (PMID 25501064, 2014). "Of these 10 patients with hyperglycaemia after pancreatectomy, 4 (9%) required insulin therapy transiently." (PMID 24840042, 2014). "This is partly attributable to the continued use of sliding-scale insulin regimens to manage severe or acute hyperglycemia, despite many treatment guidelines, recommending against its use." (PMID 25181406, 2014). "As a whole, these results suggest that hyperglycemia inhibits the influx of critical complement components to the site of S. aureus infection, but insulin rescue can improve the influx of complement components compared with persistent hyperglycemia." (PMID 25610878, 2014). "iPSCs can differentiate into insulin-producing cells responding to glucose stimulation, thereby improving the hyperglycemia in T1DM and T2DM mouse models." (PMID 25364723, 2014).
Hyperglycemia (continued). "ERK1/2 is required for stimulation of insulin gene expression under the normal physiological range of glucose concentrations, whereas chronic hyperglycemia for more than 24 h inhibits insulin gene transcription in an ERK1/2-dependent manner." (PMID 24897113, 2014). "Hyperinsulinemic-euglycemic clamping indicates insulin resistance by 8–10 weeks of age, before onset of hyperglycemia and hyperinsulinemia." (PMID 25473963, 2014). "Beta-cell specific overexpression of Reg3β driven by rat insulin promoter-1 protected mice from hyperglycemia in the streptozotocin-induced model of type 1 diabetes." (PMID 24587207, 2014). "T2D is characterized by defective insulin secretion from the pancreatic β-cells and diminished insulin sensitivity in peripheral tissues leading to hyperglycemia." (PMID 24594974, 2014). "Apart from the extension of IHIO, baseline insulin sensitivity seemed to be important for the development of intraoperative hyperglycemia." (PMID 25295519, 2014). "Diabetes is a complex metabolic disorder characterized by abnormalities in insulin secretion and action, which leads to hyperglycemia." (PMID 25147566, 2014). "The further in vitro and in vivo study showed that BJSME improved insulin sensitivity, reduced hyperglycemia, and resumed insulin levels, at least in part, by activating GLUT4 translocation." (PMID 25258641, 2014). "Nonetheless, we find that like humans and other mammals, ferrets exhibit whole-body responsiveness to insulin and exhibit a first phase peak of insulin secretion in response to sustained hyperglycemia." (PMID 24594704, 2014). "When both insulin types were combined, subjects with postprandial type hyperglycemia tended to have more hypoglycemias (p = 0.055)." (PMID 23880900, 2014). "The use of sliding-scale insulin regimen is discouraged as it only attempts to treat severe or acute hyperglycemia after it has occurred." (PMID 25181406, 2014). "Islet GFP mRNA levels were unchanged after 4 weeks of chronic hyperglycaemia, despite the reduction in islet insulin immunostaining, insulin mRNA (~50%) and insulin content (~70%)." (PMID 25145789, 2014). "In subjects using NPH insulin, there was a tendency toward a greater decrease in HbA1c in fasting type hyperglycemia group compared with postprandial type hyperglycemia group (p = 0.075)." (PMID 23880900, 2014). "Even though hyperglycemia with NPH insulin had some protective actions on islets in ITD, islet areas and BC mass were still smaller than VTD (ITD)." (PMID 24842144, 2014). "Maternal overnutrition produces maternal hyperglycemia, which increases fetal insulin secretion in a way similar to that observed in gestational diabetes." (PMID 25093191, 2014). "The incidence of hyperglycaemia requiring definitive insulin therapy increased from 13% immediately post-pancreatectomy to 77% at 7 years and then to 96% at 11 years post-surgery." (PMID 24840042, 2014). "With respect to glucose metabolism, insulin diminishes hepatic gluconeogenesis primarily by activating hepatic Akt, and this mechanism is essential for preventing the development of hyperglycemia." (PMID 26237474, 2014). "We were able to observe changes in glucose and insulin levels in obese animals, noting hyperglycemia and hyperinsulinemia in the model." (PMID 25324698, 2014). "Glucokinase activity in the pancreas is critical in enhancing insulin release in response to hyperglycaemia." (PMID 24731772, 2014). "As in dox-184ob mice, 04ob mice exhibited severe hyperglycemia as a result of diminished insulin levels and β cell mass and ultimately contributed to weight loss." (PMID 24361012, 2014). "In high-carbohydrate diet-induced insulin resistant mice, these two thiazolidin-4-ones attenuated hyperglycemia, hyperinsulinemia, hypertriglyceridemia, hypercholesterolemia, and glucose intolerance." (PMID 24995315, 2014).
Hyperglycemia (continued). "Endothelial function was measured at the myocardial level with positron emission tomography (PET) in insulin-requiring diabetic patients and postprandial hyperglycemia was targeted with various kinds of insulin regimens." (PMID 24742256, 2014). "Dickinson and colleagues studied postprandial hyperglycemia and insulin sensitivity after a 75 gram carbohydrate challenge in 60 lean, healthy individuals from five ethnic groups with similar age, BMI, waist circumference, and birth weight distributions." (PMID 24744783, 2014). "The use of a sliding-scale insulin regimen among T2DM patients with severe or acute hyperglycemia admitted to our institution was common." (PMID 25181406, 2014). "According to a published local study, 12% and 83% of admitted patients treated with sliding-scale insulin had at least one episode of hypoglycemia and hyperglycemia, respectively." (PMID 25181406, 2014). "The metabolic syndrome and T2DM are characterized by a compromised ability of insulin to control glucose disposal in muscle, increased hepatic glucose production, and overt postprandial hyperglycemia." (PMID 25279796, 2014). "It is mainly characterized by chronic hyperglycemia, resulting from defects in insulin secretion and insulin action." (PMID 24772450, 2014). "High-dose insulin (HDI) (using doses 10-fold greater than traditional therapy for hyperglycemia) is an emerging therapeutic modality for PICS." (PMID 24713415, 2014). "Since hyperglycemia in these mice is required for detectable adaptation of grafted islets, the increased demand for insulin in this model is expected to be a potent stimulus for beta cell adaptation in the islet graft." (PMID 23441226, 2013). "T2DMis a complex heterogeneous group of metabolic disorders including hyperglycemia and impaired insulin action and/or insulin secretion, in which genetic factors play a complex and yet not clearly defined role." (PMID 23671871, 2013). "Exogenous insulin or sulphonylurea (SU)-based therapies, while valuable in reducing hyperglycaemia, continue to act even after an ideal glucose concentration has been met and therefore pose the risk of over-correction and hypoglycaemia." (PMID 22776039, 2013). "Our results suggest that xylazine-induced hyperglycemia results from the decrease of tissue sensitivity to insulin, which leads to the reduction of tissue glucose uptake and utilization." (PMID 24138083, 2013). "We conclude that xylazine administration induces hyperglycemia in normoglycemic and insulin-dependent diabetic monkeys potentially via stimulation of α2-adrenoceptors and then reducing tissue sensitivity to insulin and glucose uptake." (PMID 24138083, 2013). "In our model, the regenerating beta-cells are protected from hyperglycemia either with transplanted islets or insulin implants; the latter situation more closely resembling the treatment of diabetic patients." (PMID 23762423, 2013). "STZ rats previously administered with nicotinamide exhibited moderate hyperglycemia as the consequence of partial reduction of beta cells mass and impaired insulin secretion." (PMID 23691181, 2013). "For example, TUDCA administration to obese and diabetic mice has been shown to normalize hyperglycemia, insulin sensitivity, resolve fatty liver disease, and enhance insulin action in liver, muscle and adipose tissues." (PMID 23667647, 2013). "Photoreceptoral responses were of higher amplitude in the untreated diabetic animals as compared to congenic controls some weeks after the onset of hyperglycemia and fell abruptly within two hours of insulin treatment." (PMID 23408985, 2013). "It has been proposed that the restoration of both the early phase of insulin release and postprandial hyperglycemia have potentially significant implications in improving metabolic control and reducing macrovascular complications." (PMID 24215809, 2013).
Hyperglycemia (continued). "In all groups, except group F, hyperglycemia was controlled with a subcutaneous insulin pellet on day 1 (repeated if subsequent blood glucose values ≥250 mg/dL on 2 consecutive readings)." (PMID 23405091, 2013). "We adopt a step-down approach when a patient presents with marked hyperglycemia (for example, HbA1c ≥9.0%) in which case insulin, unless poorly tolerated or contraindicated, is combined with or without metformin." (PMID 23841986, 2013). "Hyperglycemia-induced TNFα levels promote insulin resistance in retinal Müller cells, noted through increased phosphorylation of IRS-1Ser307 and IRTyr960." (PMID 23592917, 2013). "The predominant mechanism linking sterol metabolism to hyperglycemia is likely to be low insulin sensitivity." (PMID 23840693, 2013). "This usually occurs when the patient has adequate BG concentrations at night and early morning, but experiences daytime hyperglycemia, in which case treatment with insulin only is recommended." (PMID 24011173, 2013). "It has been reported that chronic exposure of neonatal rats to Cd (1 mg/kg/day) significantly disturbed glucose homeostasis and destroyed pancreatic islets insulin secretion as reflected by the development of hyperglycemia." (PMID 23405080, 2013). "The exact treatment of hyperglycemia with insulin can return glomerular hypertrophy and hyperfiltration partially." (PMID 25340133, 2013). "Several approaches are described to reduce the hyperglycemia, such as treatment by sulfonylureas, which stimulates pancreatic islet cells to secrete insulin and metformin, reducing the hepatic glucose production." (PMID 23737820, 2013). "These promote insulin resistance, gluconeogenesis, and glycolysis and impair insulin secretion, resulting in intraoperative stress-induced hyperglycemia." (PMID 23837943, 2013). "Compensatory insulin secretion was preserved and hyperglycemia prevented by exercise was characterized by enhanced insulin secretion per islet and the prevention of severe depletion of islet insulin stores." (PMID 23542897, 2013). "Even in well-managed patients, daily injection of insulin cannot match the natural precise timing and dosing of insulin secretion from the pancreas in response to hyperglycemia, resulting in severe complications." (PMID 23662132, 2013). "Because of the severe hyperglycaemia, the diabetic models need to be monitored for blood glucose and administrated insulin." (PMID 23844375, 2013). "For example, in diabetic db/db mice, chronic exendin-4 administration resulted in fasting serum insulin concentrations notably higher than with vehicle treatment under conditions of hyperglycemia." (PMID 23256660, 2013). "Four weeks of cyclosporine treatment increased blood glucose levels and decreased insulin levels, but cotreatment with ginseng ameliorated the cyclosporine-induced glucose intolerance and hyperglycemia." (PMID 24009697, 2013). "Our results also demonstrate MSC transplantation to reduce hyperglycemia, hyperlipidemia and improve peripheral tissue insulin-mediated glucose uptake." (PMID 24007410, 2013). "Compared with the insulin-dependent diabetic monkeys, the decline of xylazine-induced hyperglycemia was faster and blood glucose returned to the pre-xylazine level within 90 min in normoglycemic monkeys." (PMID 24138083, 2013). "Although insulin is cardioprotective via a preconditioning-mimetic effect, its salutary effect in the setting of acute hyperglycemia disappeared." (PMID 24371503, 2013). "In contrast, β-cells in normal animals respond to hyperglycemia by near instantaneous secretion of stored insulin." (PMID 23826312, 2013). "Hyperglycemia negates the protective effect of ischemic preconditioning and, most importantly, appears to interfere with the salutary effects of insulin." (PMID 24371503, 2013).
Hyperglycemia (continued). "One possible explanation is that the definition and severity of stress hyperglycemia is difficult in diabetic patients because they are more likely to receive insulin or oral hypoglycemic agents before admission for myocardial infarction." (PMID 24090250, 2013). "Insulin production in many of these studies was inadequate to fully correct postprandial hyperglycemia in diabetic animals." (PMID 23826312, 2013). "Alpha-2 agonists diminish insulin release from the pancreas and thus promote hyperglycemia, an action of routine prominence in the horse." (PMID 24103634, 2013). "Hyperinsulinemic-euglycemic clamping indicated peripheral insulin resistance at 10 weeks of age in prehyperglycemic males, with hepatic insulin resistance developing with hyperglycemia at 16 weeks of age." (PMID 23671854, 2013). "The inability of injected glucose to raise serum insulin levels despite inducing marked hyperglycemia raised the possibility of a potential incretin effect in the refeeding response." (PMID 23861810, 2013). "This has implications for insulin treatment of hyperglycemia in diabetic patients, as it has been described in humans as well as rodents that initiation of insulin therapy leads to weight gain that is characterized by an increase in adiposity." (PMID 24069458, 2013). "The American Diabetes Association (ADA) established a link between high intake of soluble dietary fiber and improved hyperglycemia and insulin secretion in T2D patients." (PMID 23662132, 2013). "The currently available treatment options for hyperglycemia, apart from lifestyle changes and weight reduction, are oral hypoglycemic agents (OHAs) with various modes of action, and different types of insulin." (PMID 23737820, 2013). "The majority of them were targeted to emphasize the ameliorating effect of hyperglycemia either by increasing insulin secretion or by sensitizing downstream signaling." (PMID 23662125, 2013). "Studying infants who did not receive insulin therapy allowed us to investigate the role of hyperglycemia in the incidence of ROP independently of insulin exposure." (PMID 23679669, 2013). "Following our approach using neonatal porcine liver-derived cells, we were able to obtain functional insulin-producing cells capable of lowering hyperglycemia in diabetic animals." (PMID 24260156, 2013). "Mice fed a HF diet have greater islet mass, accumulation of fat within the pancreas, hyperglycemia, and high plasma insulin and beta cell mass, resulting in a high HOMA-IR." (PMID 23894285, 2013). "Insulin gene therapy has been shown to induce remission of hyperglycemia within a few days of treatment in rodent models of type 1 diabetes." (PMID 24348585, 2013). "Exercise is known to reduce overall metabolic risk factors, improving lipid metabolism and lowering blood pressure in patients with high blood pressure, reducing insulin resistance, and improving hyperglycemia." (PMID 24472469, 2013). "Immunohistochemical analysis of the STZ pancreata at one month post transplantation revealed very low numbers of insulin-positive cells and all cured mice that were nephrectomised reverted to severe hyperglycaemia (blood glucose ≥33.7 mmol/l)." (PMID 23451276, 2013). "Glucose disposal is mediated by the conjoint effect of insulin and hyperglycemia to modulate three basic phenomenon." (PMID 23671867, 2013). "Insulin has anti-inflammatory properties that can attenuate the pro-inflammatory effect of hyperglycemia." (PMID 23776669, 2013). "Fatty acid composition of serum phospholipids were measured in 11 type 1 diabetic patients after a day of hyperglycemia and after normoglycemia was reestablished by insulin infusion." (PMID 24195588, 2013). "Such hyperglycemia is most likely via xylazine stimulation of α2-adrenoceptors and subsequent reduction of tissue sensitivity to insulin and glucose uptake." (PMID 24138083, 2013).